TREM2 (triggering receptor expressed on myeloid cells 2)
Diseases named in the same sentence as TREM2 in open-access papers (continued):
Sharing a sentence is not in itself a finding about the gene and the disease.
neurodegenerative disease (continued). "Collectively, understanding the mechanism by which the Trem2 R47H variant affects myeloid cell function and pathology across multiple disease models promises to decipher common mechanisms by which myeloid cells modulate neurodegenerative disease pathology." (PMID 29859094, 2018). "Because the TREM2/DAP12-mediated signal is a dominant switch that transforms microglia from a homeostatic to a disease-associated state, it is likely that dysregulation of TREM2/DAP12 signaling contributes to the pathogenesis of neurodegenerative diseases, including AD." (PMID 30127720, 2018). "Besides AD, TREM2 variants have been linked to other neurodegenerative diseases, including ALS, PD and FTD." (PMID 30532704, 2018). "Although coding variants of TREM2 are linked to the risk of neurodegenerative diseases, the underlying mechanisms remain unknown." (PMID 29587871, 2018). "Therefore, a comprehensive analysis of all TREM2 variants will be essential to understanding TREM2 function in both neurodegenerative diseases and other inflammatory diseases, and to design targeted therapies accordingly." (PMID 27995897, 2016). "In this sense, deficiencies in key genes for microglial survival and/or proliferation (such as CSF1R or TREM2) are associated with rare hereditary neurodegenerative diseases, such as adult-onset leukoencephalopathy with axonal spheroids or Nasu–Hakola disease (respectively)." (PMID 27743026, 2016). "For example, rare mutations in the triggering receptor expressed on macrophages-2 (TREM2) gene are associated with an increased risk of developing neurodegenerative diseases including AD, and many mouse models of familial Alzheimer’s display alterations in Trem2 expression." (PMID 27918464, 2016). "TREM2 mutations linked to neurodegenerative disease—loss of function or gain of toxic function?" (PMID 26337043, 2015). "Understanding the lifecycle of this receptor will determine whether, and how, these processes are affected by TREM2 mutations linked to neurodegenerative disease." (PMID 26337043, 2015). "Collectively, these findings highlight the complex interplay between TREM2 genetic variants and the regulation of sTREM2 production, underscoring the importance of further research to better understand these mechanisms and their implications for neurodegenerative diseases." (PMID 40247363, 2025). "Given the significance of TREM2 variants in neurodegenerative disease and impaired microglial functioning, our findings indicate that the interaction between NMES and KLOTHO deficiency may be explained by a dysfunction in signaling processes necessary for immune recovery." (PMID 40869172, 2025). "Moreover, Nurr1 deficiency resulted in a significant proportion of DAM-like phenotype microglia, which is a recently identified subpopulation characteristically associated with neurodegenerative diseases, as determined by the changes of Cx3cr1, Itgax, Trem2, and Tmem119." (PMID 37990334, 2023). "TREM2 plays a critical role in microglial function, including phagocytosis, cytokine production and cell survival, and genetic evidence has linked TREM2 to neurodegenerative diseases including ALS, but its function in ALS pathogenesis is largely unknown." (PMID 38001994, 2023). "The inheritance of the most common TREM2 variant, R47H (arginine to histidine at position 47), impairs ligand binding and confers a markedly increased risk for developing late-onset AD and other neurodegenerative diseases, such as amyotrophic lateral sclerosis, frontotemporal dementia, and PD." (PMID 35582645, 2022). "Interestingly, the activation of Akt in response to CSF1 in Trem2-deficient microglia indicates that CSF1 may be a potential therapeutic molecule for TREM2-loss-of-function neurodegenerative disease." (PMID 33841415, 2021).
neurodegenerative disease (continued). "Low-frequency variants in TREM2 have been reported to increase AD risk by almost 3–4 times, and, therefore, investigating the functional roles of such variants may be crucial to understanding the involvement of TREM2 in various neurodegenerative diseases." (PMID 34576031, 2021). "Meanwhile, wild-type and mutant TREM2 are successfully produced based on expression systems in mammalian cells for structural and biophysical studies, which is critical for understanding the functional consequences of TREM2 mutations associated with the development of neurodegenerative diseases." (PMID 35003116, 2021). "This might be one of the major mechanisms underlying various neurodegenerative diseases with advanced age by suppression of WT TREM2 in many sporadic cases, considering that TREM2 variants associated with loss-of-function are extremely rare in frequency in humans." (PMID 32959884, 2020). "In addition, because the TREM2 R47H variant confers risk for other neurodegenerative diseases, this study also provides a basis for understanding important myeloid cells functions and provides potential avenues for therapeutic targets in other disease contexts." (PMID 29859094, 2018). "To uncover potential additional mechanisms of Trem2 in neurodegenerative diseases, particularly neuroinflammation, we employed wild-type BV-2 microglia and Trem2-overexpressing BV-2 cells as models." (PMID 39997067, 2025). "MS4A6A regulates soluble TREM2 (sTREM2), influencing neuroinflammation in Alzheimer's, and genetic variations in its locus exacerbate inflammation in neurodegenerative diseases." (PMID 41239018, 2025). "Addressing these challenges is essential for effectively exploiting TREM2’s therapeutic potential for neurodegenerative diseases." (PMID 40940798, 2025). "In various mouse models of neurodegenerative diseases and human brain samples, researchers have discovered that TREM2 activation induced by apoptotic neurons triggers the APOE signaling pathway." (PMID 40722268, 2025). "Conversely, stimulating TREM2 signalling augments microglial proliferation and certain forms of reactivity in neurodegenerative disease models." (PMID 40400621, 2025). "Despite the close functional connection between TREM2 and DAP12, the potential contribution of TYROBP variants to neurodegenerative diseases remain inconclusive." (PMID 40301889, 2025). "Our results support claims of TREM2 as an important receptor acting from the periphery in neurodegenerative disease." (PMID 39472664, 2025). "Conversely, the overexpression of TREM2 has been shown to alleviate spatial cognitive deficits and suppresses inflammatory cytokine production in a mouse model of AD, suggesting that TREM2 activation is protective in neurodegenerative diseases such as AD." (PMID 41208869, 2025). "TREM2 protein is highly expressed in the brain and plays an active role in the activation of microglia in the central nervous system (CNS) homeostasis, suggesting that TREM2 dysfunctions can be significantly involved in AD and other neurodegenerative diseases." (PMID 40806186, 2025). "Both in vitro and in vivo studies have demonstrated decreased TREM2 expression across several neurodegenerative diseases models, including ALS." (PMID 40346540, 2025). "Recent evidence indicates that certain natural compounds exhibit therapeutic potential for neurodegenerative diseases such as AD by modulating TREM2-related molecular pathways." (PMID 40940798, 2025). "Genes linked to neurodegenerative diseases, such as GPNMB, GBA, CD33, and TREM2, were downregulated in ALI‐CO‐iMG 60d compared with 60d iMG." (PMID 41221983, 2025). "This review analyzed the structure and function of TREM2 and its influence on microglia, synthesizing our current understanding of its role in neurodegenerative diseases, particularly AD, with an additional focus on PD and ALS." (PMID 40940798, 2025).
neurodegenerative disease (continued). "According to literature findings, TREM2 has previously been found to play an important role in the function of microglia in neurodegenerative diseases." (PMID 40548122, 2025). "Despite the considerable focus on the TREM2 signaling pathway's regulation of immune cells in neurodegenerative diseases and tumors, its role in peripheral inflammatory diseases remains largely uncharted." (PMID 40552184, 2025). "This review comprehensively examines the multifaceted roles of TREM2 in neurodegenerative diseases, evaluates its therapeutic potential, and provides direction for developing innovative immunometabolic interventions." (PMID 40940798, 2025). "TREM2 holds significant promise as a therapeutic target for neurodegenerative diseases, demonstrating considerable potential in drug development and treatment strategies." (PMID 40940798, 2025). "TREM2 is specifically expressed in microglia, and its expression is increased in various neurodegenerative diseases." (PMID 40459937, 2025). "The TREM2-APOE signaling axis plays a crucial role in regulating the DAM/MGnD phenotype of microglia in neurodegenerative disease models." (PMID 40722268, 2025). "This review examines the functions of TREM2 in neurodegenerative diseases and its potential as a therapeutic target, aiming to inform future treatment strategies." (PMID 40940798, 2025). "In athe realm of neurodegenerative diseases, TREM2 activation not only bolsters microglial survival and functionality but also enhances their phagocytic prowess." (PMID 40552184, 2025). "Owing to its ability to bind to various ligands, the function of Trem2 has attracted extensive research interest, with a focus on central neurodegenerative diseases, especially Alzheimer’s disease (AD)." (PMID 41460571, 2025). "By reducing shedding, it increases the surface expression of TREM2, leading to enhanced Syk phosphorylation and calcium signaling, thereby potentially slowing the progression of human neurodegenerative diseases." (PMID 40242752, 2025). "Triggering receptor expressed on myeloid cells 2 (TREM2) is a protein that is primarily expressed in myeloid cell types in the brain and has emerged as a significant player in AD and other neurodegenerative diseases as well as a promising therapeutic target." (PMID 39273614, 2024). "Our work highlights the potential of ASOs as a research tool to study the functions of APOE and TREM2 in neuroinflammation and as a potential therapeutic modality to interfere with the role of microglia and neuroinflammation in neurodegenerative diseases." (PMID 38654375, 2024). "TREM2 confers neuroprotective functions against neuronal injury in a variety of neurodegenerative diseases." (PMID 38348765, 2024). "Our comprehensive binding studies highlight the surfaces that TREM2 utilizes to engage multiple ligands within the scope of neurodegenerative diseases." (PMID 39315272, 2024). "Simultaneously, TREM2 has witnessed significant breakthroughs in various fields, including inflammation, aging, and neurodegenerative diseases 38-42." (PMID 39113887, 2024). "TREM2 also has been reported to exhibit increased expression in neurodegenerative diseases such as AD." (PMID 39201760, 2024). "DAM express multiple genes related to AD and other neurodegenerative diseases, including triggering receptor expressed on myeloid cells 2 (TREM2), a receptor essential for DAM activation." (PMID 39710713, 2024). "Currently, a wealth of research has provided evidence that activating TREM2 on microglia promotes the clearance of myelin debris and remyelination in neurodegenerative diseases." (PMID 37815901, 2024). "The triggering receptor expressed on myeloid cells-2 (TREM2) plays a central role in regulating myeloid cell maturation and function in the setting of numerous human pathologies, including neurodegenerative diseases, metabolic diseases, and cancers." (PMID 39315272, 2024).
neurodegenerative disease (continued). "Previous studies have demonstrated that TREM2 is vitally important to microglial phagocytosis during brain development and neurodegenerative diseases." (PMID 39544929, 2024). "Genes implicated in both monogenic neurodegenerative disease and risk genes are related to microglia and immune pathways, such as APOE, TREM2, and TBK1, many of which were also identified in our microglial transcriptomic and proteomic data." (PMID 38923692, 2024). "This knowledge holds significant therapeutic potential, guiding the development of targeted treatments to modulate TREM2 function in neurodegenerative disease management." (PMID 39159814, 2024). "Regulation of neuroinflammation, inhibition of microglial exosome synthesis and secretion, altering microglial metabolism, altering the microglial phenotype, and TREM2 activation are potential therapeutic strategies in treating neurodegenerative diseases." (PMID 37735487, 2023). "Soluble TREM2 can be observed in body fluids, mainly by shedding from the cell surface, serving as a potential biomarker of microglia activation in neurodegenerative diseases." (PMID 36755323, 2023). "Based on this contradictory evidence, TREM2 appears to exert anti-inflammatory or proinflammatory effects depending on its stimulus or aging-related neurodegenerative disease." (PMID 37998347, 2023). "Since TREM2 is known to bind to other pathologically accumulated proteins in neurodegenerative disease, the relationship between TREM2 and α-syn should be further considered." (PMID 36768798, 2023). "Triggering Receptor Expressed On Myeloid Cells 2 (TREM2) is a membrane protein expressed on immune cells, involved in neurodegenerative diseases and cancer." (PMID 36627355, 2023). "It should be noted that microglial activation occurs in two steps, the first of which is TREM2-independent, and the second of which is TREM2-dependent, which emphasizes the critical function of TREM2 in the development of neurodegenerative diseases." (PMID 37510803, 2023). "TREM2 has been extensively studied in microglial cells that exert anti-inflammatory properties and promotes phagocytosis of apoptotic neuronal cells in neurodegenerative diseases." (PMID 37566293, 2023). "TREM2 exerts anti-inflammatory effects and promotes apoptotic neurons in many diseases, including neurodegenerative diseases, ischemia/reperfusion injury, and bacterial infections phagocytosis." (PMID 36672106, 2023). "To further explore the spatiotemporal dynamics of microglial activation, we focused on the mechanism involving triggering receptors expressed on myeloid cells 2 (TREM2), which has been reported in neurodegenerative disease models." (PMID 35682897, 2022). "Soluble fragment of triggering receptor expressed on myeloid cells 2 (sTREM2) in cerebrospinal fluid (CSF) is a biomarker of microglial activation and increased in several neurodegenerative diseases." (PMID 35783125, 2022). "Triggering receptor expressed on myeloid cells 2 (Trem2) plays a protective role in neurodegenerative diseases." (PMID 36333761, 2022). "TREM2 has been extensively studied in microglia and neurodegenerative diseases and recently emerged as a marker of pro-tumorigenic macrophages." (PMID 35746551, 2022). "Further, dystrophic neurites in normal aging and neurodegenerative diseases lead to a phenotype switch from homeostatic to neurodegenerative microglia (MGnD) by stimulating the TREM2-APOE pathway." (PMID 36698776, 2022). "In microglia, TREM2 was reported to be enriched in the disease-associated microglia (DAM) subset, which accumulates during neurodegenerative diseases." (PMID 35746551, 2022). "In neurodegenerative diseases with abnormal protein aggregates, TREM2 as a kind of lipid-sensor in microglia, is a genetic susceptibility factor for AD." (PMID 36742201, 2022).
neurodegenerative disease (continued). "DAM microglia has both immunosuppressive and inflammatory effects in neurodegenerative disease and triggering receptor expressed on myeloid cells 2 (TREM2) was involved in this progress." (PMID 35803929, 2022). "In recent years, the role of TREM2 in neurodegenerative diseases has rapidly become an interesting area of active studies." (PMID 35003116, 2021). "Triggering receptor expressed on myeloid cells 2 (TREM2) is an innate immune cell surface receptor that regulates microglial function and is involved in the pathophysiology of several neurodegenerative diseases." (PMID 33881612, 2021). "In recent years, strong evidence of a link between TREM2 function in the innate immune system and the pathogenesis of neurodegenerative diseases has been documented." (PMID 33881612, 2021). "TREM2, MERTK and AXL have all been implicated in myelin debris clearance during certain neurodegenerative diseases." (PMID 33924200, 2021). "Trem2 maintains microglial immune fitness, enhancing the ability to engulf misfolded protein aggregates through the modulation of metabolic machinery in neurodegenerative diseases." (PMID 32903682, 2020). "Trem2 maintains microglial survival and activation, which is challenged during neurodegenerative diseases." (PMID 32903682, 2020). "Mutations in triggering receptor expressed on myeloid cells 2 (Trem2) and granulin (GRN) are associated with various neurodegenerative diseases, and these genes are dysregulated in the majority of recently identified microglial phenotypes." (PMID 32903682, 2020). "Two main receptors have been identified as key regulators in the generation of these particular phenotypes in neurodegenerative diseases: Toll-like receptors (TLRs) and triggering receptors expressed on myeloid cells-2 (TREM2)." (PMID 33203002, 2020). "This study supports previous findings and provides additional insight of the mechanism responsible for loss of ligand binding, which is critical to our understanding of the role of TREM2 in neurodegenerative diseases." (PMID 32107424, 2020). "All of the TREM2 genetic linkage studies with neurodegenerative diseases suggest an important contribution of impaired or decreased TREM2 function in regulating microglial functions contributing to disease progression." (PMID 32959884, 2020). "TREM2 has been also found to bind LPS, which is the most well-characterized bacterial-derived molecule in neurodegenerative disease models." (PMID 33203002, 2020). "Numerous studies have revealed that TREM2 exerts anti-inflammatory properties and promotes phagocytosis of apoptotic neuronal cells in neurodegenerative diseases, liver ischemia/reperfusion injury, and bacterial infections." (PMID 32466767, 2020). "Together, this suggests that abnormal TREM2 function plays an essential role across different neurodegenerative diseases." (PMID 30630532, 2019). "Our findings refine understanding of the impact of point mutations on the structural stability of TREM2 and give credence to a role for the apical CDR in neurodegenerative disease." (PMID 32021611, 2019). "One example of this concept can be explained with the gene coding for the triggering receptor expressed on myeloid cells 2 (TREM2) and genetic risk factors in different neurodegenerative diseases." (PMID 30743990, 2019). "Nevertheless, these results provide compelling new evidence that TREM2 acts as a master switch, that regulates the activity and function of microglia in AD and other neurodegenerative diseases." (PMID 30618585, 2018). "These genetic findings have attracted attention to the role of microglia in neurodegenerative diseases and TREM2 in regulating microglial function." (PMID 30532704, 2018). "Mouse modeling studies show increased TREM2 expression in multiple models of neurodegenerative diseases, and TREM2‐positive microglial cells appear to surround plaques in APP models." (PMID 30341064, 2018).